MIR1302-9 (microRNA 1302-9)
Synonyms: hsa-mir-1302-9
Gene: MicroRNA gene on chromosome 9 (30,144 to 30,281, forward strand). Ensembl gene ENSG00000283921.
Gene Ontology:
Biological process: miRNA-mediated post-transcriptional gene silencing
Homologues: Paralogues in human: MIR1302-10 (100% identical), MIR1302-11 (100% identical), MIR1302-2 (100% identical).